ACSL4 (acyl-CoA synthetase long chain family member 4)
Diseases named in the same sentence as ACSL4 in open-access papers (continued):
Sharing a sentence is not in itself a finding about the gene and the disease.
ischemic stroke (continued). "Suppression of the thrombin-ACSL4 pathway may reduce neuronal ferroptosis following ischemic stroke." (PMID 37373168, 2023). "Since the free AA in the hippocampus of mice increased significantly after ischemic stroke, these data further indicate that the decrease of ACSL4 during I/R may be the result of a post-translational modification." (PMID 35197442, 2022). "Here we found that the thrombin–ACSL4 axis promotes ferroptotic cell death after ischemic stroke, and pharmacologically inhibiting this pathway may provide a new avenue for therapy." (PMID 35197442, 2022). "Acyl-CoA synthetase long-chain family member 4 (ACSL4) is considered a target of ferroptosis, but its specific role in ischemic stroke remains unclear." (PMID 33889074, 2021). "Although ACSL4 is considered a sensitive monitor and an important contributor to ferroptosis, its specific role in ischemic stroke is unknown." (PMID 33889074, 2021). "Hence, there is a need for better understanding the function and significance of ACSL4 in ischemic stroke and its relationship with ferroptosis." (PMID 33889074, 2021). "Additionally, in a mouse model of ischemic stroke, ACSL4 is upregulated after ischemia–reperfusion, and blocking ACSL4 via small-molecule inhibitors (e.g., rosiglitazone) reduces iron accumulation, oxidative stress, and ferroptotic markers, thereby improving neurological recovery." (PMID 41516398, 2026). "For example, a recent ferroptosis study pointed out that thrombin can induce ACSL4-dependent ferroptosis during cerebral ischemia/reperfusion, which suggested thrombin-ACSL4 axis may be an important therapeutic target to ameliorate ferroptotic neuronal injury during ischemic stroke." (PMID 36507355, 2022). "Therefore, the thrombin-ACSL4 axis may be a key therapeutic target to ameliorate ferroptotic neuronal injury during ischemic stroke." (PMID 35197442, 2022). "Moreover, thrombin was shown to induce ferroptotic signaling by promoting arachidonic acid mobilization and the subsequent esterification of ACSL4, suggesting that targeting the thrombin/ACSL4 axis may alleviate ischemic stroke via ferroptosis inhibition." (PMID 36358568, 2022). "Acyl-CoA synthetase long-chain family member 4 (ACSL4) and glutathione (GSH), two regulators of ferroptosis, show different expression patterns during recovery from ischemic stroke." (PMID 40949877, 2025). "Melatonin mitigates ferroptosis and neuronal damage in ischemic stroke models, an effect achieved through the MDM2-mediated ubiquitination and degradation of ACSL4, leading to a reduction in ferroptosis markers like intracellular Fe2+." (PMID 41306421, 2025). "Growing evidence suggests that ACSL4 and LOX, especially 12/15-LOX, are increased in ischemic stroke." (PMID 36425577, 2022). "Increasing evidence has demonstrated the involvement of ACSL4 and LOX in ischemic stroke." (PMID 39042604, 2024). "ACSL4 overexpression, GPX4 inhibition and GSH downregulation in ischemic stroke lead to lipoxygenase activation, Ca2+ influx, mitochondrial membrane rupture and inhibition of ferroptosis, effectively attenuating mPTP opening and leading to mitochondrial dysfunction." (PMID 38026442, 2023). "A recent study showed that acyl-CoA synthetase long-chain family member 4 (ACSL4), an isozyme for polyunsaturated fatty acids (PUFAs) metabolism, was a novel regulator of ferroptosis and significantly influence the recovery of ischemic stroke." (PMID 36967397, 2023). "Additionally, the amount of MDA and the mRNA expression level of ACSL4 and GPX4 were significantly different between ischemic stroke patients and healthy participants, which was consistent with these results identified in mice." (PMID 36967397, 2023). "Thus, interventions involving the ACSL4 pathway in defending against ferroptosis might provide a novel therapeutic strategy for ischemic stroke." (PMID 38026442, 2023).
liver cancer (29 papers, 2016 to 2026). An epithelial or non-epithelial malignant neoplasm that arises from the liver. "A previous study reported a strong association between ACSL4 expression and fatty liver disease as a risk factor leading to liver cancer." (PMID 39335604, 2024). "The enzyme acyl‐CoA synthetase long‐chain family member 4 (ACSL4), associated with fatty acid metabolism, has emerged as a key player in the progression of liver cancer in recent studies." (PMID 39268355, 2024). "ACSL4 disorders are associated with a variety of malignant tumors, including gastric, breast and liver cancer." (PMID 36313708, 2022). "An overexpression of ACSL4 frequently predicts a poorer prognosis for patients with colon and liver cancers." (PMID 40932861, 2025). "Current research has indicated that ACSL4 can serve as a biomarker for predicting the sensitivity of sorafenib treatment in liver cancer patients." (PMID 40932861, 2025). "This approach would enable the reflection of ACSL4 expression levels in liver cancer tissues by detecting miRNAs in plasma." (PMID 39563427, 2024). "It has been reported that miR-23a-3p directly targets ACSL4 to regulate ferroptosis to improve sorafenib resistance and inhibit liver cancer." (PMID 37008632, 2023). "In this study, researchers also found that blocking HK2 or ACSL4 effectively inhibited cancer progression, which provides a promising therapeutic strategy for the treatment of liver cancer." (PMID 36497375, 2022). "Meanwhile, compared with normal tissues, ACSL4 was strongly positive in endometrial cancer and liver cancer, and low in breast, lung, and renal cell carcinoma tissues in the human protein atlas." (PMID 35126480, 2022). "ACSL4 is not only enhanced during ferroptosis but also required for cells to undergo ferroptotic cell death, at least in leukemia and liver cancer cells." (PMID 35963845, 2022). "Blocking HK2 or ACSL4 effectively inhibits liver cancer growth, and GalNac‐siHK2 administration specifically targets the growth of orthotopic tumor xenografts." (PMID 35603967, 2022). "To explore the effects and reveal the underlying mechanism of ACSL4 in the progression of HCC, we first determined ACSL4 expression pattern in liver cancer tissues and cells." (PMID 32357142, 2020). "Notably, in vitro experiments have shown that KLF1 enhances liver cancer cell proliferation by inhibiting ferroptosis, and this inhibition is negatively correlated with the transcription levels of fatty acid synthase 4 (ACSL4)." (PMID 41656392, 2026). "Studies have indicated that tumors exhibiting high ACSL4 expression, such as certain triple-negative breast cancers and liver cancers, may demonstrate increased sensitivity to RSL345." (PMID 41372608, 2025). "The elevated levels of ACSL4 in these tumors, particularly in colon and liver cancers, could potentially enable targeted induction of ferroptosis in tumor tissues." (PMID 40932861, 2025). "However, the expression of ACSL4 is complicated, as ACSL4 is not only elevated during ferroptosis but also required for cells to undergo ferroptotic cell death in leukemia and liver cancer cells." (PMID 39462426, 2024). "For example, ACSL4 is highly expressed in patients with liver cancer and colon cancer, and the higher the expression level is, the worse the prognosis is, while patients with gastric cancer tend to have a low expression of ACSL4." (PMID 37373168, 2023). "Hexokinase 2 (HK2) could activate the transcription of ACSL4, leading to an increase in fatty acid β-oxidation activity which could promote liver cancer growth." (PMID 36497375, 2022). "Commonly, in ACSL4 high expressing cancers (e.g., colon or ovarian cancer), increased expression of ACSL4 typically predicts unfavorable outcome/prognosis, while in the ACSL4 low expressing cancers (e.g., liver cancer), decreased expression of ACSL4 is corelated to unfavorable outcome/prognosis." (PMID 35910359, 2022).
liver cancer (continued). "In addition, inhibitors of ACSL4 expression attenuate the proliferation of a cultured liver cancer cell line." (PMID 32286604, 2020). "ACSL4 is also overexpressed in liver cancer tissues compared with the corresponding normal tissue." (PMID 27171439, 2016). "Therefore, ACSL4 is expected to be a target for liver cancer treatment." (PMID 40148434, 2025). "Notably, it has been shown that blocking the transcription of ACSL4 can effectively inhibit the growth of liver cancer, suggesting that ACSL4 may act as a pro-oncogene." (PMID 39652084, 2025). "Therefore, ACSL4 is considered a potential target for liver cancer treatment." (PMID 40148434, 2025). "TOP2A, CENPF, ACSL4, SPARC, and COL4A5 were significantly upregulated in patients with liver cancer, while they were downregulated by CTD treatment in HCC cells." (PMID 38017425, 2023). "The results showed that the level of ACSL4 is increased in cholangiocarcinoma (CHOL), colon cancer, head and neck cancer, liver cancer and stomach cancer." (PMID 37193981, 2023). "A large number of studies have shown that ncRNAs can affect the progression of liver cancer by mediating various ferroptosis-related classical molecules or signals, such as SLC7A11, GPX4, and ACSL4." (PMID 37065473, 2023). "After evaluating the correlation of these fatty acid‐related genes with the ES cell‐like gene expression signatures in HCC, we found that four genes, including ACSL3, ACSL4, FADS1, and FADS2, were highly related to stem cell characteristics in liver cancer." (PMID 35603967, 2022). "Of note, AKR1B10, ACSL4, GLS2, LCAT, were among the metabolic targets we previously identified as consistent in HCC, indicating a high alteration frequency of these genes across liver cancer datasets." (PMID 30176945, 2018). "However, the mechanism by which ACSL4 regulates BA metabolism through FXR and further impacts M2 macrophage polarization and liver cancer progression remains unclear." (PMID 39268355, 2024). "Therefore, ACSL4 knockout may protect mice from developing NASH, which can lead to liver cancer." (PMID 39335604, 2024).
lung carcinoma (29 papers, 2016 to 2025). "Although most studies revealed that the low expression of ACSL4 in lung cancer was a biomarker of adverse outcomes, some studies showed that the upregulation of ACSL4 gene may be one of the causes of lung cancer." (PMID 35910359, 2022). "The ACSL family has been implicated in lung cancer, with elevated expression of ACSL3 and ACSL4 observed in this disease." (PMID 41288931, 2025). "The CPT1A/c-Myc signaling axis reduces lipid peroxide generation in lung cancer cells by suppressing ACSL4 expression and concurrently enhances resistance to ferroptosis through stimulation of the NRF2/GPX4 antioxidant pathway." (PMID 39875356, 2025). "Curcumin promotes ferroptosis, thereby inhibiting lung cancer tumor growth, by upregulating ACSL4 and downregulating ferroptosis-inhibiting genes (SLC7A11 and GPX4)." (PMID 38892270, 2024). "Curcumin enhances the ferroptosis of lung cancer cells by upregulating the ferroptosis-inducing ACSL4 gene." (PMID 38892270, 2024). "Targets such as Nrf2, LSH, STYK1/NOK, and ACSL4 also hold significant promise in the field of ferroptosis in lung cancer." (PMID 39944353, 2024). "LncRNA NEAT1 can target ACSL4 and inhibit the protein expression of ACSL4, thus regulating the sensitivity of lung cancer cells to ferroptosis." (PMID 37005430, 2023). "When ACSL4 is upregulated, lipid peroxidation products and lethal reactive oxygen species accumulate, thus sensitiating lung cancer cells to ferroptosis." (PMID 37005430, 2023). "Small ubiquitin-like modifier (SUMO) specific protease 1(SENP1) can regulate A20 by desumoylation, and then inhibit ferroptosis of lung cancer cells by affecting the interaction between A20 and ACSL4, SLC7A11." (PMID 37005430, 2023). "The results showed that ACSL4 was highly dependent on leukemia, bladder cancer, lymphoma and lung cancer cell lines." (PMID 35126480, 2022). "Another critical mediator of the proferroptotic cascade, ACSL4, is downregulated in bladder, brain, breast, leukemia and lung cancer but upregulated in colorectal, head and neck, kidney, myeloma and liver cancer." (PMID 35118067, 2021). "In contrast, brain, breast and lung cancer patients with low ACSL4 expression have a poor survival, suggesting that ACSL4 plays different roles in different cancer types." (PMID 35118067, 2021). "The co-expression profiles for ACSL4 in breast, brain, colorectal and lung cancer were analyzed from Oncomine." (PMID 27171439, 2016). "The prognostic analysis indicated that the colorectal patient with higher ACSL4 expression had poor survival; in contrast, the brain, breast, and lung cancer patient with lower ACSL4 expression had poor survival." (PMID 27171439, 2016). "For instance, a study in A549 and H1299 lung cancer cells reported that OA treatment led to the upregulation of ACSL4 and downregulation of GPX4, accompanied by elevated ROS levels and enhanced lipid peroxidation, ultimately accelerating ferroptosis cell death." (PMID 41301966, 2025). "Additionally, circ_SCN8A enhances the expression of fatty acid-binding protein 4 (ACSL4) by binding to miR-1290, promoting lung cancer cell proliferation and migration, and inhibiting ferroptosis." (PMID 39139574, 2024). "This study confirmed that OA could inhibit SDC4 expression and promote the occurrence of ferroptosis in A549 cells and H1299 cells through the GPX4/ACSL4 pathway, providing an effective basis for the use of drugs targeting ferroptosis in lung cancer treatment." (PMID 39400975, 2024). "ACSL4 was universally expressed in the lung cancer cell lines in our study." (PMID 38539505, 2024). "Taken together, our data suggest that ACSL1 may be a potential diagnostic marker for lung ADC, and that ACSL1, ACSL4, and ACSL5 may be involved in lung cancer differentiation." (PMID 38539505, 2024). "Since ACSL4 promotes ferroptosis in lung cancer cells, it can be speculated that the inhibition of ACSL4 by TC might result in reduced levels of ferroptosis." (PMID 38539505, 2024).
lung carcinoma (continued). "In addition, we confirmed the increase in mRNA and protein levels of ACSL3 and ACSL4 in brain and lung cancer cells, which was similar with the iTRAQ data, illustrating that ferroptotic markers are upregulated by NCI677397." (PMID 38140768, 2024). "A previous study indicated that a combined high ACSL4 level and low-dose 256-slice spiral CT may be a potential biomarker for the screening of early lung cancer, and high ACSL4 indicates a better prognosis than low ACSL4 levels." (PMID 39335604, 2024). "When ACSL4 is knocked down in vitro, the survival rate and invasiveness of lung cancer cells are enhanced, on the contrary, overexpression would promote ferroptosis of lung cancer cells." (PMID 37005430, 2023). "Therefore, targeting ACSL4 is an effective way to promote ferroptosis in lung cancer." (PMID 37005430, 2023). "In addition, we detected the expression of 4HNE and ACSL4 in different lung cancer cell lines." (PMID 36153508, 2022). "Beyond ACSL3 and ACSL4, ACSL5 has been reported to influence lung cancer cell behavior by modulating the effects of lysophosphatidylcholine through the remodeling of transcriptional regulators." (PMID 41288931, 2025). "ACSL4 and ACSL5 were downregulated in the majority of lung cancer cell lines, except for an upregulated ACSL4 in H226, H2030, and H1975 and increased ACSL5 levels in COLO677, H322, H1650, and H1975, compared to the NHBE cells." (PMID 38539505, 2024). "We found that, compared to normal human bronchial epithelial (NHBE) cells, ACSL1, ACSL4, and ACSL6 were highly expressed, while ACSL3 and ACSL5 were lost in the majority of lung cancer cell lines." (PMID 38539505, 2024). "MPE collected from lung cancer patients with pleural metastasis stimulated the expressions of GPX4, FTL, and NUPR1, whereas decreased the expression of ACSL4 in both A549 and H1975 cells." (PMID 37649596, 2023). "Studies have shown that SENP1 can modulate the inflammatory signal A20, which interacts with ACSL4 and SLC7A11 to regulate ferroptosis in lung cancer cells." (PMID 36639654, 2023). "To investigate the anticancer effect and mechanism of OA on lung cancer, we first stimulated lung cancer cells with OA in vitro and observed its changes and further analyzed the role of ferroptosis, the SDC4 gene, and the glutathione peroxidase 4 (GPX4)/ACSL4 signaling pathway." (PMID 39400975, 2024). "In human lung cancer cells, we found that the proteins of ACSL1, ACSL4, and ACSL6 were highly expressed in most of the lung cancer cell lines observed, while the proteins of ACSL3 and ACSL5 were lost in the majority of the lung cancer cell lines, compared to the NHBE cells." (PMID 38539505, 2024). "Taken together, the data suggest that ACSL1 may be a biomarker for lung ADC, and ACSL1, ACSL4, and ACSL5 may be involved in lung cancer differentiation, and TC, in combination with chemotherapy or EGFR-TKIs, may help patients overcome drug resistance." (PMID 38539505, 2024). "Different from lung cancer, ACSL1‐5 is highly expressed in ATI of COPD as the representative of lung chronic inflammation, ACSL1 and 3 in ATI and basal cells of IPF as fibrosis and ACSL4 in ATI cells of SSC as a systemic immune disorder." (PMID 36639836, 2023). "However, a few analyses gave the inconsistent trend in one cancer, including the outcome of ACSL3 in lung cancer of GSE13213 and GSE31210 datasets, the expression of ACSL4 in Buchholz and Badea pancreatic cancer datasets, and the expression of ACSL5 in Hou and Okayama lung cancer datasets." (PMID 27171439, 2016).